SELENBP1 (selenium binding protein 1)
Diseases named in the same sentence as SELENBP1 in open-access papers (continued):
Sharing a sentence is not in itself a finding about the gene and the disease.
Alzheimer disease (1 paper, 2025). A progressive, neurodegenerative disease characterized by loss of function and death of nerve cells in several areas of the brain leading to loss of cognitive function such as memory and language. "In T1DM, some of the terms annotated were related to myelin dysregulation (ARHGEF6, CNP, NADK2, PSAP, SLC25A12) and other neurological disorders, such as Alzheimer’s disease (i.e., POA2, APOC1, APOC3, CNP, GSK3B, PON1, PSAP, SELENBP1) or movement disorders." (PMID 39901093, 2025).
amyloid (1 paper, 2024). "BCAN, MDH1, PCOLCE and SELENBP1, to our knowledge, have not previously been implied in CAA/amyloid pathology." (PMID 38191511, 2024).
autism (1 paper, 2022). Persistent deficits in social interaction and communication and interaction as well as a markedly restricted repertoire of activity and interest as well as repetitive patterns of behavior. "Consistent with other studies, we also observed that SELENBP1 was lower in ASD children than in TD children, which indicates that low selenium levels is a risk indicator for autism." (PMID 36761165, 2022).
autism spectrum disorder (1 paper, 2022). A spectrum of developmental disorders that includes autism, and Asperger syndrome. "We also analyzed copy number variations (CNVs) in two SELENBP1-overexpressing PFC samples and found a partial overlap of these CNVs with the CNVs of long non-coding RNAs (lncRNAs) of autism spectrum disorder (ASD)-related genes." (PMID 36512497, 2022).
cervical cancer (1 paper, 2023). A primary or metastatic malignant neoplasm involving the cervix. "Accordingly, knockdown of SELENBP1 in HeLa cervical cancer cells decreased ROS levels and enhanced GPx-1 expression." (PMID 38001780, 2023).
coronary artery spasm (1 paper, 2025). "SELENBP1 (selenium-binding protein 1) and vinculin (VCL) were recently analyzed in cases of death caused by coronary artery spasm, proving their reliability in such instances." (PMID 40725061, 2025).
cutaneous melanoma (1 paper, 2018). A primary melanoma arising from atypical melanocytes in the skin. "This discovery raises the hypothesis that SELENBP1 functions as tumor suppressor in cutaneous melanoma." (PMID 29535818, 2018).
dyslipidemia (1 paper, 2021). "As dyslipidemia is a known dioxin-induced toxicity, a possible association with Selenbp1 can be postulated." (PMID 34069420, 2021).
hepatitis B virus infection (1 paper, 2020). A viral infection caused by the hepatitis B virus. "Other clinicopathological factors, such as information on the diagnosis of hepatitis B virus infection, gender, and tumor grades, had no relevance with SELENBP1 expression." (PMID 32443734, 2020).
hepatobiliary tumors (1 paper, 2022). "The regulatory involvement of SELENBP1 in EMT has been reported in hepatobiliary tumors but remains to be elucidated in CRC and other malignancies." (PMID 36117772, 2022).
inflammatory bowel disease (1 paper, 2024). A spectrum of small and large bowel inflammatory diseases of unknown etiology. "A previous study aimed to identify biomarkers of intestinal repair by large-scale screening of multiple transcriptomic and scRNA-seq datasets of patients with inflammatory bowel disease (IBD) and identified 10 marker genes that potentially contribute to intestinal barrier repairing and SELENBP1." (PMID 39728443, 2024).
leiomyoma (1 paper, 2010). A well-circumscribed benign smooth muscle neoplasm characterized by the presence of spindle cells with cigar-shaped nuclei, interlacing fascicles, and a whorled pattern. "The expression of selenium-binding protein 1 was the same among patients with proliferative, secretory, and atrophic endometrium in either leiomyoma or normal myometrium." (PMID 21143902, 2010). "Both Western Blot analysis and immunohistochemistry showed a significant lower level of selenium-binding protein 1 in leiomyoma than in normal myometrium." (PMID 21143902, 2010). "However, the level of SELENBP1 was significantly lower in leiomyoma than in normal myometrium either in patients younger than 45 years or in older patients." (PMID 21143902, 2010). "It is likely that additional genetic and molecular events contribute to tumorigenesis, but reduction of SELENBP1 expression may be a key step in the transition from normal myometrium to leiomyoma." (PMID 21143902, 2010). "Since the effects of selenium are mediated by SELENBP1, loss of SELENBP1 expression in leiomyoma may have a negative impact on the ability of selenium to control tumor cell growth." (PMID 21143902, 2010). "Indeed, decreased expression of SELENBP1 in even the smallest leiomyoma (i.e., 1 cm) examined suggests that alteration in SELENBP1 expression may be an early event in the development of the tumor." (PMID 21143902, 2010). "Our study demonstrated similar levels of SELENBP1 among patients with proliferative, secretory, and atrophic endometrium in either normal myometrium or leiomyoma, indicating that SELENBP1 is not regulated by sex hormones." (PMID 21143902, 2010). "When the expression of SELENBP1 is reduced, however, leiomyoma may develop because selenium without adequate SELENBP1 may be incapable of inhibiting the stimulatory actions of estrogens." (PMID 21143902, 2010).
lentivirus infection (1 paper, 2023). Virus diseases caused by the Lentivirus genus. "And the stable SELENBP1‐overexpressing A549 and H1299 cell lines and control cell lines were established by lentivirus infection." (PMID 37606338, 2023).
metastatic colorectal cancer (1 paper, 2025). "Other studies have confirmed strong correlations between Helicobacter cinaedi and Sphingobium herbicidovorans in metastatic colorectal cancer tissues with specific genes (such as SELENBP1 and SNORA38), providing new ideas for personalized treatment." (PMID 40852612, 2025).
migraine (1 paper, 2024). "Although our review did not specifically identify MRPS21 and SELENBP1, functional clustering analysis in our study revealed a close association between migraine and mitochondrial dysfunction and oxidative stress, with corresponding support from transcriptomic, proteomic, and metabolomic data." (PMID 39850553, 2024). "Furthermore, in 2024, the Hautakangas team conducted a meta-analysis of three GWAS studies on migraine, confirming multiple risk loci, including TNF-α, MRPS21, and SELENBP1, which are closely linked to inflammatory responses, mitochondrial function, and oxidative stress." (PMID 39850553, 2024).
myocardial ischemia (1 paper, 2019). A disorder of cardiac function caused by insufficient blood flow to the muscle tissue of the heart. "The fast appearance of SELENBP1 already during surgery and the linear relationship between circulating SELENBP1 and the duration of myocardial ischemia suggests that SELENBP1 may have been released by cardiomyocytes upon stress and before necrosis." (PMID 31450690, 2019).
myopia (1 paper, 2009). "Selenbp1 expression can be blocked by TGF-β in smooth muscle cells and this protein (TGF-β) has already been implicated in myopia and in the regulation of programmed cell death in the retina." (PMID 20019881, 2009).
Nephropathy (1 paper, 2025). A nonspecific term referring to disease or damage of the kidneys. "Moreover, increased expression of SELENBP1 in glomerular mesangial cells during nephropathy has been shown to promote inflammation, aligning with observations regarding enhanced liver inflammation in our current study." (PMID 40298842, 2025).
pulmonary arterial hypertension (1 paper, 2025). Pulmonary arterial hypertension (PAH) is a group of diseases characterized by mean pulmonary artery pressure >20 mmHg and elevated pulmonary arterial resistance leading to right heart failure. "Conversely, decreased SELENBP1 contributes to the risk of pulmonary arterial hypertension." (PMID 40298842, 2025).
renal carcinoma (1 paper, 2019). A carcinoma arising from the epithelium of the renal parenchyma or the renal pelvis. "Several analyses have quantified SELENBP1 in tumor tissues and report on reduced SELENBP1 expression levels in association with poor survival in gastric, breast and renal cancer." (PMID 31450690, 2019).
skin cancer (1 paper, 2022). "Skin cancer: SELENBP1 concentration remains low in skin carcinoma." (PMID 36386843, 2022).
squamous cell carcinoma (1 paper, 2016). A carcinoma arising from squamous epithelial cells. "Twenty-nine cancer samples and 30 margin samples were collected from patients undergoing surgical ablation of Larynx squamous cell carcinoma, the relative expression of SELENBP1 gene was lower in beginning and advance of tumor stage than in margin (P < 0.01)." (PMID 27583873, 2016).
tumor (57 papers, 2009 to 2025). "Previous studies have shown the tumor-suppressive role of selenium-binding protein 1 (SBP1), but the underlying mechanisms are unclear." (PMID 25974208, 2015). "Decreased expression of one of RGN's coexpression partner SELENBP1 which encodes a selenium-binding protein, has also been shown to be associated with multiple tumour types." (PMID 24523864, 2014). "Among the two patients who received R-chemotherapy, one (MC4) gained additional mutations (SELENBP1) in relapse based on pretreatment dominant tumor clones, whereas the other (MC206) acquired mutations (CD70 and ZFP36L1) from a minor and undetected pretreatment tumor clone." (PMID 40876452, 2025). "However, SELENBP1, which is considered a tumor suppressor, is often downregulated in tumor tissues, and this has been epidemiologically linked to poor clinical outcomes." (PMID 37760083, 2023). "SELENBP1 expression was significantly associated with tumor size and gross typing." (PMID 36117772, 2022). "This suggests that the prognostic impact of SELENBP1 mRNA expression level in CRC patients may be associated with tumor immune infiltration to some extent." (PMID 36253721, 2022). "This type of screening for SELENBP1/MTO may be of interest as low SELENBP1 levels in tumor tissue are associated with poor prognosis for patients." (PMID 33901808, 2021). "Additionally, the molecular mechanisms underlying the tumor-suppressive role for SELENBP1 in cancer cells are still largely undefined." (PMID 31918717, 2020). "For patients, low SELENBP1 levels in tumour tissue are associated with poor prognosis." (PMID 30469030, 2019). "SELENBP1 down-regulation is associated with tumor progression as well as poor clinical outcome." (PMID 29535818, 2018). "SELENBP1 is encoded by a gene located at 1q21.3 near the epidermal differentiation complex, which is closely related to the terminal differentiation of the human epidermis and contains genes that encode the S100A family members (associated with tumor progression and metastasis)." (PMID 39728443, 2024). "Tumors derived from SELENBP1-overexpressing cells exhibited significantly reduced growth compared to controls, further supporting its tumor-suppressive role in LUAD." (PMID 40787454, 2025). "In contrast, low expression of NEDD4L (OS: HR = 0.75, RFS: HR = 0.59, PPS: HR = 0.53) and SELENBP1 (OS: HR = 0.65, RFS: HR = 0.56, PPS: HR = 0.64) was associated with poor prognosis, suggesting a protective role by inhibiting tumor progression." (PMID 40959565, 2025). "Conversely, ectopic overexpression of SELENBP1 suppressed tumor growth by enhancing apoptosis, reducing intracellular ROS accumulation, and impairing in vivo xenograft progression." (PMID 40787454, 2025). "The tumor-suppressive role of SELENBP1 was also experimentally validated, providing mechanistic insights and therapeutic implications." (PMID 40787454, 2025). "SELENBP1 is reported as a tumor suppressor frequently downregulated across multiple cancers and has been linked to redox homeostasis and lipid/glucose metabolism in vivo." (PMID 41411367, 2025). "Proteomic analysis of preoperative and postoperative peripheral blood samples from patients undergoing tumor resection revealed a significant upregulation of SELENBP1 and a significant downregulation of SEPP1." (PMID 38397459, 2024). "To further confirm the function of SELENBP1 on the growth of NSCLC cells in vivo, we established a stable SELENBP1‐overexpressing A549 cells tumor xenograft model in athymic nude mice via subcutaneous injection as we previously reported." (PMID 37606338, 2023). "SELENBP1 has long been known for its anti-proliferative actions as tumor suppressor that is down-regulated in many types of cancer." (PMID 37437449, 2023). "On the other hand, SELENBP1, which generates H2S through the oxidation of methanethiol, is often downregulated in tumor tissue." (PMID 37760083, 2023).
tumor (continued). "Our findings highlighted that SELENBP1 was an important tumor suppressor during the origin and development of NSCLC." (PMID 37606338, 2023). "Meanwhile, we also performed an analysis of SELENBP1 expression in 50 tumor samples and their matched adjacent tissues." (PMID 36253721, 2022). "To characterize the potential mechanism of SELENBP1 in inhibiting tumor progression, we first used the combined TCGA COAD and READ dataset to conduct a GSEA and found that high SELENBP1 expression was negatively correlated with the hallmark EMT gene set." (PMID 36117772, 2022). "In the current study, we demonstrated that SELENBP1 has tumor-suppressive roles both in vitro and in vivo, in consistent with observations from other researchers." (PMID 36117772, 2022). "The heat map combined with the difference in GSVA scores showed that SELENBP1 expression was negatively correlated with multiple cancer species-related pathways like Tumor proliferation signature, Cellular response to hypoxia, EMT markers, TGFB, etc.." (PMID 36253721, 2022). "This study confirmed the active involvement of SELENBP1 in tumor progression of CRCs via modulating the EMT." (PMID 36117772, 2022). "It has been shown to regulate tumor cell growth and metastasis via a variety of downstream target genes, including Selenbp1, EGFR, Foxa2, CDX2, and DDB1." (PMID 36614938, 2022). "SELENBP1 is therefore a candidate tumor suppressor, which should be further investigated in future studies." (PMID 36117772, 2022). "SELENBP1 expression in CRC patients affects patient prognosis by influencing tumor immune infiltration." (PMID 36253721, 2022). "With increasing SELENBP1 expression, immune and stromal components in the tumor microenvironment were significantly decreased." (PMID 36253721, 2022). "SELENBP1 has been functionally involved in tumor prognosis and malignancy, and evidence has indicated SELENBP1 to be a tumor suppressor." (PMID 36362053, 2022). "SELENBP1 is a direct target for transcription factor Nkx2-1, which can inhibit tumor clonal growth and migration and inhibit malignant progression of LUAD in vivo." (PMID 34604392, 2021). "These new risk factor results are particularly important since the SEPP1 gene product has recently been shown to be in the same metabolic pathway as a tumor suppressor (Selenium binding Protein 1) for prostate cancer." (PMID 34504230, 2021). "In RCC, SELENBP1 has been proved as a tumor suppressor gene and low SELENBP1 mRNA expression predicts a worse cancer-specific survival." (PMID 35141153, 2021). "Seventy-five percent of normal liver tissues exhibit moderate (++) to strong (+++) expression of SELENBP1, whereas counterpart tumor tissues show moderate to strong at much lower rates (18.3%)." (PMID 32443734, 2020). "SELENBP1 is currently considered a tumour suppressor that regulates cell proliferation, senescence, migration and apoptosis." (PMID 32616892, 2020). "In this study, we show that SELENBP1 expression is reduced in HBx-expressing human cells and human liver tumors as compared with matched non-tumor (counterpart normal) liver tissues." (PMID 32443734, 2020). "Nevertheless, some associations with (patho-)physiological processes were described, including a link to cell differentiation and a correlation between low SELENBP1 expression levels in tumor tissue and poor clinical outcome (for review, see Ref." (PMID 31557719, 2020). "High SELENBP1 expression was observed in normal liver tissues while the expression levels of SELENBP1 were reduced in most tumor sections on the tissue microarray." (PMID 32443734, 2020). "SELENBP1 expression levels in tumor tissues and adjacent normal tissues were evaluated using immunoblotting assay." (PMID 31918717, 2020). "In 10 (out of 13) cases with elevated HBx in tumors, 80% (8/10) show reduced SELENBP1 protein expression in Western blot, and 70% (7/10) show consistent results with immunohistochemistry of tumor tissue array." (PMID 32443734, 2020).